RNU6-115P (RNA, U6 small nuclear 115, pseudogene)
Gene: Small nuclear RNA gene on chromosome 20 (15,022,852 to 15,022,958, forward strand). Ensembl gene ENSG00000201180.
Homologues: Orthologues: chimpanzee U6 (99% identical), macaque U6 (93% identical), dog U6 (77% identical), rat LOC120095710 (77% identical). Paralogues in human: RNU6-1159P (94% identical), RNU6-797P (90% identical), RNU6-16P (88% identical), RNU6-41P (88% identical), RNU6-1123P (87% identical), RNU6-11P (87% identical), RNU6-183P (87% identical), RNU6-208P (87% identical), RNU6-379P (87% identical), RNU6-37P (87% identical), RNU6-393P (87% identical), RNU6-1047P (86% identical), and 1286 more.